IL6 (interleukin 6)
Diseases named in the same sentence as IL6 in open-access papers (continued):
Sharing a sentence is not in itself a finding about the gene and the disease.
tumor (continued). "M1-macrophages exert anti-tumor effects by promoting increased expression and release of cytokines such as IL-1β, TNF-α, IL-6, and IL-12 and elevating the helper T cell 1 (Th1)-mediated immune response." (PMID 37588995, 2023). "Tumor cells and stromal cells such as CD163+ macrophages in ascites can release VEGF, TGFβ, IL-6, IL-8, promoting neovascularization and supporting OC metastasis." (PMID 36698173, 2023). "Mutually, tumor TAMs promote CSC maintenance via soluble mediators, including interleukin-6 (IL-6) and pleiotrophin." (PMID 36969696, 2023). "OV-mediated ICD triggers the release of IL-6, IL-8, IFN-β, IP-10 (CXCL10), MCP-1 (CCL2) and KC (CXCL1) from cancer cells to recruit different immune cells and initiate an anti-tumor response." (PMID 36831636, 2023). "Exposure of microglial cells to glioblastoma cell-derived EVs revealed an upregulation of the expression of the pro-tumor factors CXCL1/10, CCL2/CCL5 and IL-6 as well as an increase in their own proliferation." (PMID 37700840, 2023). "The level of IL-1β, IL-6 and TNF-α were increased in tumor mice after DSF treatment, while the level of IL-4, IL-10 and TGF-β were increased after DSF treatment." (PMID 37305383, 2023). "Human ADSC-secreted IL-6 significantly stimulates proliferation, EMT, transmigration, and 3D invasion of human primary normal and tumor epithelial cells." (PMID 36880535, 2023). "EDX suppressed elevated plasma levels of IL-6, MMP-2, TF, and PAI-1 and elevated tumor tissue levels of PAR2, STAT3, cyclin D1, and Ki67 in Colon26-inoculated mice." (PMID 36751299, 2023). "The IL-6/JAK/STAT3 pathway is aberrantly over-activated in many types of cancer and drives tumor cell proliferation, survival, invasion, and metastasis, while it strongly suppresses antitumor immune responses." (PMID 37835536, 2023). "Significantly increased mitogenic cytokine IL6 and TNF levels were noted in advanced fibrosis, leading to a propensity towards cancer by regulating immune cells and the growth of tumor cells." (PMID 37628834, 2023). "Multiple cell types in the tumor microenvironment produce IL-6, leading to activation of JAK/STAT3 signaling in both tumor and tumor-infiltrating immune cells." (PMID 37686695, 2023). "Downregulated NF-κB further contributes to reduce the secretion of IL-6, TGF-β1, VEGF, and IL-17A in tumor cell and increase the level of regulatory T cells that collectively inhibits the progression of epithelial ovarian cancer." (PMID 37822929, 2023). "Previous studies have shown that multiple cytokines, including IL-6 and IL-10, activate their receptors on GBM cells to promote tumor progression, whereas IL-7 reduces tumorigenicity and enhances the immune responses of CD8+ T cells." (PMID 37734869, 2023). "Even though IL-6 is mainly a pro-inflammatory cytokine, it can recruit MDSC cells to the tumor site and therefore promote the tumor immune escape." (PMID 37568571, 2023). "MSCs can also enhance tumor vascularization by upregulating VEGF and IL-6, and promote the progression and metastasis of cancer by secreting CCL5, CCL7, and TGF-β." (PMID 37666813, 2023). "Studies in a rat model of CRC demonstrated that (3R)-falcarinol and (3R,8S)-falcarindiol, isolated from carrots selectively, inhibited the expression of COX-2 in tumor tissue as well as TNF-α and IL-6, thus explaining the CRC-preventive effect of carrots." (PMID 37894640, 2023). "The micelle formulation inhibited tumor growth in the C57BL/6 mouse model by inducing robust anti-tumor immune responses, such as higher levels of TNF-α, IL-12, and IL-6 than the control group." (PMID 36986636, 2023). "We also showed significantly increased IL-6, IL-7, and GM-CSF levels in the supernatants of CAR133-i502-NK92 cells co-cultured with tumor cells." (PMID 37731205, 2023). "Mo0 stimulated the release of cytokines and chemokines such as IL6, IL1A, CXCL1, CXCL5, and CCL20, which can induce monocyte recruitment to tumor." (PMID 37675100, 2023).
tumor (continued). "IL-6, secreted by CAFs, promotes STAT3 activation and, thus, tumor invasion and metastasis formation." (PMID 37371856, 2023). "Exosomal transfer and paracrine signaling, by cytokines, including IL6 and GM-CSF, have been demonstrated as another mechanism of CAF-tumor cell interaction." (PMID 38234683, 2023). "In the case of HeLa cells, they produce proinflammatory cytokines such as TNF-α, IL-6, IL-2, IL-12, and IFN-γ to sustain tumor development and proliferation over the long term." (PMID 37767520, 2023). "At 9 months of age, all HDAC3LCKO&IL-6−/− female mice developed spontaneous HCC (100%, 11/11), while only over half of HDAC3LCKO&IL-6−/− males developed tumours (65%, 9/14)." (PMID 37752418, 2023). "The authors reported distant tumor inhibition, DCs maturation, high infiltration of CD3+ and CD8+ T cells, increased secretion of INF-γ, and release of TNF-α and IL-6." (PMID 37238966, 2023). "In the subset of tumor-promoting CAFs, iCAFs can participate in immune escape or directly act on pancreatic cancer cells by producing inflammatory cytokines such as IL-6, leukemia inhibitor factor (LIF), and CXCL1 to promote tumor progression." (PMID 37666813, 2023). "Several cytokines secreted by macrophages, including TNF-α, IL-6, and IL-8, have the potential to induce EMT in tumor cells, thereby promoting metastasis." (PMID 38139154, 2023). "In consistency with these studies, ETP-treated and F30-HSCs exhibited higher levels of pro-inflammatory gene expression, such as IL-1β, IL-6, CXCL1 and CXCL9, as well as MMPs (for tumor metastasis) than controls." (PMID 37649614, 2023). "Senescent HPMCs were proven to modulate cancer cells by secreting IL-6 and TGF-β1, promoting tumor vascularization through HIF-1α, NF-κb/p50, and AP-1/c-Jun pathways." (PMID 37046588, 2023). "First, tumor cells can secrete immunosuppressive cytokines or metabolic factors, such as transforming growth factor-β (TGF-β), interleukin-6 (IL-6), IL-10 and prostaglandin (PGE2), in an autocrine or paracrine manner to inhibit the killing of tumor cells." (PMID 37138865, 2023). "Studies on RCC with mutated VHL have shown that proinflammatory cytokines (e.g., IL-6, TNF-α, IL-1) and MMP-2 foster tumor spread and are overexpressed in more invasive cell lines." (PMID 36614308, 2023). "IL‐6 induced production of glutathione has been shown to stimulate MBM by triggering MMP‐2 enzymatic activity in the tumour microenvironment." (PMID 37759347, 2023). "Chronic inflammatory cytokines such as IL-6, IL-10 and TGF-β were found to be important in mediating the expansion and suppressive functions of MDSCs, resulting in tumor angiogenesis, development and metastasis." (PMID 37108179, 2023). "It has been found that the exposure of tumor cells to NE elicits the secretion of neuropeptide Y (NPY), which in turn facilitates the recruitment of macrophages and subsequent release of interleukin 6 (IL6)." (PMID 38089966, 2023). "Tumor-infiltrating lymphocytes are often inactivated or exhausted due to immunosuppressive factors, including cytokines (IL-6, IL-10, TGF-β, galectin-1) secreted by tumor, stromal, and myeloid immune cells." (PMID 38087370, 2023). "While CD8+ T cell depletion significantly restored tumor growth in mice receiving dual IL-6/CTLA-4 blockade, CD4+ depletion resulted in pronounced tumor growth." (PMID 36881480, 2023). "In this study, a combination of anti-IL-6 and anti-Tim-3 treatments produced a synergistic effect to enhance cytotoxic CD8+ T activity in the tumor microenvironment." (PMID 37193819, 2023). "In B16F10 tumor-bearing mice, GRo significantly inhibited tumor growth, LPS-induced lung damage, and TNF, IL-6, and IL-1 transcript levels in tumor tissues." (PMID 38139116, 2023). "IL-6 acts through JAK-STAT signaling pathways, but the effects are dependent on the cells present and the specific context of the tumor microenvironment." (PMID 37514190, 2023).
tumor (continued). "According to the Eta correlation test, the difference levels of IL6, CA-125, and HE4 between groups with tumor resectability of suboptimal > 1 cm and optimal < 1 cm also showed a strong positive correlation to the tumor resectability." (PMID 37792745, 2023). "CAAs increase the secretion of IL-6 and leptin, which activate the JAK/STAT3 axis in BC cells and reduce the sensitivity of tumor cells to the toxic effects of NKs." (PMID 36765683, 2023). "IL-6 secreted by TAMs activates the JAK/STAT3 pathway, promotes tumor survival, invasion, and angiogenesis, and mediates the epithelial-mesenchymal transition (EMT)." (PMID 38017494, 2023). "IL-6/STAT3 as well as the IL-2/STAT5 pathway activates downstream target genes to protect tumour cells from apoptosis, increase tumour cell proliferation, cell cycle progression, invasion, and metastasis, and are involved in drug resistance." (PMID 36980202, 2023). "In agreement with these functions, our MPM AFs showed increased expression of IL-6, IL-17A, PDGFs, various FGFs and IGF-1, all molecules reported to improve the survival and chemoresistance of tumour cells through their cross-talk with CAFs." (PMID 37938546, 2023). "Recent studies have found a correlation between increased serum levels of IL-6 and sIL-6R in patients with CRC and tumor size as well as poor prognosis in those with metastatic colorectal cancer." (PMID 37664052, 2023). "The SCC microenvironment is rich in IL-6, IFN-γ, TGF-β, GM-CSF, and IL-24, which induce tumor growth and invasion." (PMID 36793738, 2023). "IM CAFs create an immunosuppressive environment within the tumor through secreting CXCL12, TGF-β, GAS6, IL-6, HGF, GDF15, and FGF5, each of which promote cancer cell invasion, proliferation, and immunosuppression." (PMID 37626931, 2023). "Several cytokines like interleukin-6 (IL-6), IL-12, IL-8, monocyte chemoattractant protein-1 (MSC-1), activator protein-1 (AP-1) and reactive oxygen species (ROS) involved in inflammation and tumour progression are elevated and upregulated by AT1R." (PMID 37153428, 2023). "To summarize, chromium appears to induce carcinogenic processes by inhibiting the tumor suppressor miR-143, leading to activation of proangiogenic mediators such as HIF1-α and IL-6." (PMID 37593220, 2023). "According to RT-qPCR analysis, the expression of the pro-tumor macrophage markers CD206, CD163, IL-6, IL-10, Arginase-1, and TGF-β were downregulated compared to the normal control group." (PMID 38098044, 2023). "BCSC interacting with macrophages initiates their tumor-promoting function, and these TAM produce high levels of IL6, which in turn initiates activation of the STAT3 signaling pathway and consequent enrichment of BCSC." (PMID 37445860, 2023). "There was a significant difference in IL-6 (1328 vs 752 pg/ml; p<0,001), CA-125 (1260,5 vs 819,5 U/ml; p<0,001), and HE4 levels (1320 vs 760 pmol/L; p<0,001) between patients with tumor resectability of > 1 cm (suboptimal) vs < 1 cm (optimal)." (PMID 37792745, 2023). "IL-6 and IL-10 cytokines activate STAT3 on T cells, which is usually related to poor cytotoxicity and anti-tumor immune response." (PMID 36911202, 2023). "Negative regulation of the IL-6/JAK2/STAT3 signaling pathway enhanced apoptosis and autophagy in tumor cells, thereby improving the therapeutic effect on GBM." (PMID 37057281, 2023). "Once transformed, cancer cells can release EVs that contain pro-inflammatory factors, such IL-6 and TNF-α, which can activate signaling pathways in stromal cells and promote their migration to the tumor site." (PMID 38052753, 2023). "IL-6 activates JAK/STAT3 signaling, which drives tumor proliferation, survival, invasiveness, angiogenesis and immunosuppression." (PMID 37709737, 2023). "Treatment of pancreatic tumors with anti-IL6 antibodies reduces M2 macrophages, increases sensitivity to PD1 therapy, and leads to tumor regression." (PMID 37367892, 2023).
tumor (continued). "On the other hand, IL-1β, IL-6, IL-8, IL-10, IL-12, MCP-1, MIP-1β increased high grade tumor compared to low grade tumor." (PMID 37520880, 2023). "Exosomal miR-21 and IL-6 produced from CAFs together increased MDSC formation in oesophageal squamous cell carcinoma by activating STAT3, which made tumour cells resistant to cisplatin." (PMID 37569598, 2023). "Several classical signaling pathways, such as IL-6/signal transducer and activator of transcription (STAT3), HIF1/VEGFA, and PI3K/AKT, have been shown to regulate tumor angiogenesis." (PMID 36720310, 2023). "Cytokines in the tumor microenvironment (TME), such as TGF-β1 and IL-6, have also been reported to promote the stemness of various cancer cells." (PMID 38098005, 2023). "CXC motif chemokine ligand 2 (CXCL2) released by tumor cells, which in turn activates CXC chemokine receptor 2 (CXCR2), and IL-6, IL-8, and IL-1β recruit tumor-infiltrating MDSCs inducing epithelial–mesenchymal transition (EMT) and metastasis." (PMID 36831498, 2023). "M1-type macrophages produce pro-inflammatory cytokines, such as interleukin (IL)-1β, IL-6, IL-12, IL-23, and tumor necrosis factor (TNF)-β, which promote inflammatory responses and inhibit tumor growth." (PMID 37981718, 2023). "However, CD4+ T cells from the tumor-bearing and anti-IL-6 treatment alone groups reduced the cytotoxicity of the corresponding CD8+ T cells, which further demonstrated that CD4+ T cells from combination therapy could enhance the cytotoxic function of CD8+ T cells." (PMID 37108179, 2023). "Increased expression of LAG3 driven by IL6 led to decreased function of peripheral CD8 + T cells and reduced tumor therapeutic resistance." (PMID 38115039, 2023). "Increased IL-6/JAK/STAT3 signaling has been observed in different types of tumors and tumor infiltrating immune cells, as well as that this has been associated with lack of response to immunotherapy." (PMID 36720310, 2023). "Results of qPCR performed using this mRNA showed that the levels of proinflammatory cytokines, including IL-1β, IL-6, and TNF-α were significantly increased in tumor-bearing mice after DSF treatment." (PMID 37305383, 2023). "Immunosuppressive cytokines, such as IL-6 and IL-10, interfere with the antitumor effects of CD8+ and CD4+ T cells in the tumor microenvironment." (PMID 36639681, 2023). "We analyzed the cytokine milieu of the tumor microenvironment and discovered high levels of the pro-inflammatory cytokines tumor necrosis factor (TNF)-α, interleukin (IL)-1β, and IL-6." (PMID 37461742, 2023). "The IL‐6/STAT3 signaling pathway is activated by IL‐17 and directly induces VEGF release to promote tumor angiogenesis." (PMID 36951443, 2023). "Studies have shown that myeloid cell-derived S100A9 can increase blood supply and promote angiogenesis by inducing IL6 and IL10 to create a survival niche for subsequent tumor progression in multiple myeloma." (PMID 37701037, 2023). "Inhibition of either the CCR-5 or IL-6 receptor resulted in decreased tumor growth and metastatic spread, suggesting that there are three points of potential therapeutic intervention in this pathway (STAT3, IL-6, or CCR-5) for TNBC." (PMID 36768435, 2023). "The expression of ARL4C exhibited a significant and positive correlation with immune-related pathways such as TNF-α/NF-κB, INF-γ, INF-α, IL-6/JAK/STAT3, and hypoxia signaling pathways, thereby establishing a connection between ARL4C and tumor immunity." (PMID 38178862, 2023). "To define how IL-6 and IFN-γ induce chemokines by PDAC cells, we surveyed chemokine production by murine MT5 or KPC-luc tumor cells following in vitro stimulation with IFN-γ and/or IL-6 cytokines." (PMID 36881480, 2023). "More importantly, cytokines produced by tumor cells, such as VEGF, FGF, HIF-1α, and interleukin 6 (IL-6), have been shown to promote MDSC accumulation and are associated with therapeutic resistance." (PMID 36769116, 2023).
tumor (continued). "The expression levels of TNF-α, IL-6 and VEGF were all increased in patients with tumor length > 5 cm compared with patients with tumor length ≤ 5 cm, and the differences were all statistically significant (all P < 0.001)." (PMID 37430251, 2023). "Other studies have shown IL6 polarizes M2 macrophage in CRC39 and that IL6/STAT3 can form a positive feedback loop to stimulate tumor growth and progression." (PMID 37749297, 2023). "Moreover, they express effector molecules, which are destined to kill tumor cells, including perforin 1, granzyme B and TNFα, as well as multiple pro-inflammatory cytokines that are characteristic for activated macrophages and Th1 cells, including IL-1β, IL-6, IL-2 and IFNγ." (PMID 37174085, 2023). "For instance, in a mouse model for breast cancer, HFD in combination with fish oil resulted in decreased tumor weight and number, accompanied by a decrease in the pro-inflammatory markers TNF-α and IL-6 and an increase in the anti-inflammatory marker IL-10." (PMID 36830818, 2023). "Tipifarnib significantly reduced tumor nodule formation and exhibited anti-tumor and anti-inflammatory effects in a MASH-related HCC mouse model challenged with DEN and a high-fat diet (HFD), primarily by decreasing serum IL-6." (PMID 38313077, 2023). "There was a correlation between IL6 (r = 0,832), CA-125 (r = 0,716), and HE4 (r = 0,716) with tumor resectability." (PMID 37792745, 2023). "PAR1CAR-T cells secrete proinflammatory cytokines and chemokines, including TNF-α, IFN-γ, IL-1α, IL-4, IL-6, IL-17A, and GRO, upon encountering PAR1 antigens that exhibit potent cytolytic capacities against PAR1-expressing tumor cells." (PMID 37667257, 2023). "CAFs regulate tumor growth, metastasis, and angiogenesis by the secretion of transforming growth factor-β (TGF-β), IL-6, CXCL12, and chitinase-3-like-1 (CHI3L1)." (PMID 37108109, 2023). "For example, the negative correlation between patient outcome and level of tumor-associated macrophages (TAM) is reliant upon TAM expression of PDGF, TGF-β, EGF, IL-1, IL-6 and TNF-α, which generates a favorable environment for tumor growth." (PMID 37568595, 2023). "In tumor-bearing mice, PDT induced tumor growth inhibition in two different models and increased the serum levels of IFN-y, IL-6, and TNF-a after treatment." (PMID 36839652, 2023). "In further development, the Wnt signaling pathway, IL-6/STAT3 signaling pathway, changes in tumor immune microenvironment, and epithelial-mesenchymal transformation play an important role in the malignant transformation process of tissues." (PMID 38098990, 2023). "Notably, while IL-6 blockade promoted anti-tumor immunity in combination with anti-CTLA4, it ameliorated pathology driven by autoreactive Th17 responses, suggesting that IL-6/IL6R blockade may have the added benefit of attenuating immune-related adverse events." (PMID 36599350, 2023). "In pre-clinical tumor models, IL6R blockade or genetic ablation of CTL-intrinsic IL-6 signaling synergized with anti-PD-L1 therapy to enhance anti-tumor CTL responses, leading to improved tumor control." (PMID 36599350, 2023). "Our in vitro and in vivo experiments suggest that metabolic competition by glycolytic PDAC tumor cells leads to the accumulation of lactate in the TME and that CAFs utilize lactate to produce IL-6, which inhibits antitumor immunity." (PMID 37733442, 2023). "Transcript/protein pairs enriched in these pathways included inflammatory cytokines such as IL6 and IL8 as well as matrix remodeling enzymes (e.g., MMP9), indicating a tendency towards tumor invasion of the surrounding tissue." (PMID 36732562, 2023). "In one study, analysis of the “secretory phenotype” of tumor cells with activated EMT signaling revealed a distinct set of pro-inflammatory soluble factors, including IL-6, IL-8, GRO, GM-CSF, VEGF, and angiogenin." (PMID 36959556, 2023).